VEGFA (vascular endothelial growth factor A)
Diseases named in the same sentence as VEGFA in open-access papers (continued):
Sharing a sentence is not in itself a finding about the gene and the disease.
lung carcinoma (757 papers, 2002 to 2026). "Telimisartan has been shown to downregulate Bcl-2, previously associated with VEGF induction, in lung cancer cells, whereas losartan was found to inhibit Ang II-induced VEGFA and IL-8 expression in liver cancer." (PMID 41408463, 2026). "Compared to low expression, high VEGFA expression is associated with poor survival outcomes in gastric cancer, lung cancer, and colon cancer." (PMID 37852616, 2023). "LINC00941 has also been implicated in non–small cell lung cancer, where it was found to promote angiogenesis and tumor progression by sponging miR-877-3p, which is a negative regulator of VEGFA." (PMID 36869839, 2023). "The presence of immature cells in the peripheral blood of lung cancer patients have been closely associated with an increased plasma level of VEGFA, GM-CSF, M-CSF, IL-10, and TGF-β." (PMID 36230990, 2022). "We also discovered changes in the expression of new targets of FZD9, including EZH2, IL1β, and VEGFA, all of which are associated with lung cancer." (PMID 35924166, 2022). "Meta-analyses of 22 gene expression omnibus (GEO) databases of lung cancer implicated that patients with higher VEGFA and ANGPT2 mRNA expressions tended to have advanced stage in ADC rather than SQC." (PMID 31892982, 2020). "Given the robust association between PM exposure and VEGFA overexpression, efforts to reduce ambient air pollution could play a critical role in decreasing lung cancer incidence and mortality." (PMID 40940965, 2025). "Moreover, the increased proportions of Ki‐67+ proliferating cells and upregulated expression of VEGFA in lung cancer were associated with stimulated cell proliferation and angiogenesis, respectively." (PMID 33655712, 2021). "In our previous study, by pharmacological exploration, we have found that tumor growth can be inhibited by cell cycle inhibition and antiangiogenesis with the VEGFA epidermal growth factor receptor CASP3 AKT1 CCND1 associated with the prognosis of lung cancer patients." (PMID 33628320, 2021). "VEGFA is positively associated with ANGPT2 in lung cancer cell lines and tumor tissues of ADC." (PMID 31892982, 2020). "Here we demonstrated that BrM-CSCs mimic the pericytes by overexpressing CD146 in the brain TME, which is induced by the reactive astrocyte-derived GAS6, and exerts a potent pro-angiogenesis effect by dual effects on the VEGFA/VEGFR axis in lung cancer BrM." (PMID 41356185, 2026). "Here we found that CD146+ pericyte-like tumor cells derived from CD44+ BrM-CSCs potently exert pro-angiogenic effects through dual effects on the VEGFA-VEGFR2 axis in lung cancer BrM." (PMID 41356185, 2026). "Widely expressed in damaged vascular endothelial cells, VEGFA increases endothelial progenitor cell migration and significantly promotes angiogenesis in lung cancer." (PMID 40432889, 2025). "Taken together, these results demonstrate that PM exposure promotes VEGFA expression in lung cancer cells." (PMID 40940965, 2025). "This study provides different insights into the mechanistic link between ambient PM exposure and lung cancer progression, with a particular focus on angiogenesis and the overexpression of VEGFA." (PMID 40940965, 2025). "STK24 was recently known to promote tumorigenesis in lung cancer through STAT3/VEGFA signalling pathway." (PMID 40122572, 2025). "EGR1 plays an important role in cancer by promoting tumorigenesis through enhanced cyclin D1 expression in prostate cancer and by interacting with vascular endothelial growth factor A (VEGFA) to stimulate angiogenesis in lung cancer." (PMID 41561975, 2025). "To explore the clinical relevance of VEGFA in lung cancer progression, we analyzed data from The Cancer Genome Atlas (TCGA) and TNMplot.com." (PMID 40940965, 2025). "When compared to the vector, gene expression investigation by (qRT-PCR) revealed that the VEGFa mRNA level was lower in lung cancer cells infected with MSCV-ACE2." (PMID 39040892, 2024).
lung carcinoma (continued). "Alternatively activated macrophages expressing MRC1, TIE2 and CXCR4 also stimulate tumor relapse in a model with Lewis lung carcinoma cells and promote angiogenesis via VEGFA secretion." (PMID 38532508, 2024). "Overexpression of PVT1 partially recuperates the lung cancer angiogenesis constrained by ALKBH5 knockdown through mediating VEGFA expression." (PMID 39691597, 2024). "For NSCLC, the overexpression of EZH2 is linked to vascular endothelial growth factor-A (VEGF-A) signaling and correlates with a shorter survival time for patients, as the aggressiveness of the lung cancer cells increases." (PMID 39768352, 2024). "Meanwhile, lung cancer cells can produce less VEGFa protein and accumulate less VEGFa mRNA when ACE2 is overexpressed." (PMID 39040892, 2024). "Another study also confirmed that YTHDC2-mediated m6A methylation enhances the ability of angiogenesis in lung cancer by promoting the expression of vascular endothelial growth factor A (VEGFA)." (PMID 39033180, 2024). "miR-101-3p, which is downregulated in lung CAFs, can suppress CAF activation and target VEGFA, influencing lung cancer cell migration and invasion." (PMID 39834587, 2024). "ELISA results showed that both NFs and CAFs secreted higher amount of VEGFA than lung cancer cells, and the amount of VEGFA from CAFs was the highest." (PMID 37056933, 2023). "Angiogenesis is significantly increased in cultures that are transfected with miR-143-3p, and overexpression of miR-143-3p can increase VEGFA expression in lung cancer cells, thereby regulating angiogenesis in lung cancer tissues." (PMID 38053093, 2023). "Higher levels of Tenascin C (TNC), ICAM1, and VEGFA further supported that they were involved in pleural metastasis in lung cancer." (PMID 37649596, 2023). "VEGFA plays a crucial role in tumor progression 22; our previous study demonstrated that VEGFA secretion was responsible for the CAFs' effect on lung cancer metastasis." (PMID 37056933, 2023). "To verify this assumption, we first detected the VEGFA level released from CAFs and lung cancer cells." (PMID 37056933, 2023). "SIRT1, HIF1α and VEGFA protein expression in DDP-induced chemotherapy-resistant lung cancer tissues were declined when miR-326 was overexpressed." (PMID 34696659, 2022). "To study the mechanism of ALKBH5 in tumor angiogenesis in lung cancer cells, we first analyzed the potential m6A modification sites of VEGFA mRNA." (PMID 36376862, 2022). "We next observed that PVT1 promoted the progression of lung cancer cells in vitro and in vivo and regulated the expression of VEGFA and angiogenesis in lung cancer." (PMID 36376862, 2022). "We found that VEGFA in lung tissue of lung cancer mice is significantly higher than that in healthy mice, which means that it is beneficial to angiogenesis and growth of lung cancer cells in lung cancer tissues." (PMID 35371324, 2022). "Although ADAM9 has been shown to enhance pulmonary vascular remodeling in lung cancer via VEGFA, angiopoietin-2, and tissue plasminogen activator, there is a paucity of literature linking ADAM9 to PH." (PMID 36522710, 2022). "ADAM9 is known to increase vascular endothelial growth factor A (VEGFA) expression in lung cancer metastasis." (PMID 36404352, 2022). "For example, MB mRNA expression correlated with HIF1α (r = 0.483) or VEGFa (r = 0.468) in lung cancer tissue samples." (PMID 33996536, 2021). "Taken together, these results demonstrated that CAFs promoted metastasis potential of lung cancer cell via miR-101-3p regulated VEGFA secretion." (PMID 34977016, 2021). "Here we demonstrated that miR-101-3p inhibited VEGFA secretion from CAFs, and VEGFA mediated the effect of CAFs on migration and invasion of lung cancer cells." (PMID 34977016, 2021). "We further demonstrated that downregulation of miR-101-3p in CAFs increased VEGFA secretion, facilitating the metastasis potential of lung cancer cells via activation of Akt/eNOS signaling pathway." (PMID 34977016, 2021).
lung carcinoma (continued). "EGR1 is reported to directly initiate VEGFA expression in lung cancer cells by binding to the VEGFA promoter and to increase angiogenesis by enhancing HIF1α-mediated VEGFA expression." (PMID 33842351, 2021). "In our next study, through IHC staining, we found that IL‐36α was negatively correlated with MVD and VEGFA expression in tumor tissues of lung cancer‐bearing mice and NSCLC tissues." (PMID 33713575, 2021). "Further mechanistic study showed that downregulation of miR-101-3p in CAFs increased VEGFA secretion, facilitating the metastasis potential of lung cancer cells via activation of Akt/eNOS signaling pathway." (PMID 34977016, 2021). "Inhibition of vascular endothelial growth factor-A (VEGF-A) also induced long-term dormancy of lung cancer micrometastases by preventing angiogenic growth to macrometastases in a mouse model of brain metastasis." (PMID 34162963, 2021). "The brain metastasis of lung cancer results from m6A-mediated matured miR-143-3p upregulating the expression of VASH1 to increase ubiquitylation of VEGFA." (PMID 34295922, 2021). "Angiogenic proceed is abundant in lung cancer and the LL‐2 cells with high expression levels of bFGF and VEGFA were selected to investigate the tumor inhibition of Peptibody vaccine in vivo." (PMID 32944017, 2020). "MiR-126 acts on multiple target genes involved in lung cancer angiogenesis, such as VEGFA and epidermal growth factor-like domain 7 (EGFL7)." (PMID 33121202, 2020). "In network analysis, the hub targets of cinobufotalin injection against lung cancer were identified as VEGFA, EGFR, CCND1, CASP3, and AKT1." (PMID 32148531, 2020). "It was recently denoted that miR-126 mediates the anti-cancer effects of tubeimoside-1 by directly controlling the expression of vascular endothelial growth factor A (VEGFA) in lung cancer cells." (PMID 33066509, 2020). "Taken together, our results demonstrated that LINC00173.v1 promotes the tumorigenesis of lung cancer cells via the miR-511-5p/VEGFA signaling axis." (PMID 32473645, 2020). "Here, we demonstrated that LINC01436 regulated the expression of EPAS1 and its target genes in lung cancer cell lines, including angiogenesis (VEGFA) and metabolism reprogramming (GLUT1) genes." (PMID 30614188, 2019). "Next, we investigated the role of JAK2/STAT3/VEGFA pathway in the anti-angiogenic potential of anlotinib in lung cancer cell." (PMID 30755242, 2019). "In this study, we demonstrated that autophagy enhanced VEGFA expression of lung cancer cells via activation of JAK2/STAT3 signaling pathway both in vitro and in vivo." (PMID 30755242, 2019). "Our results showed ADAM9 silence in lung cancer cells significantly reduce the VEGFA and ANGPT2 expression." (PMID 29118335, 2017). "We show that ADAM9 promotes vascular remodeling in lung cancer cells by increasing the expression of VEGFA, ANGPT2, and PLAT." (PMID 29118335, 2017). "In our study, a higher concentration of VEGFA was detected in ADAM9-abundant lung cancer cells compared to ADAM9 knockdown cells and resulted in higher angiogenesis in endothelial tube formation assays." (PMID 29118335, 2017). "In another model of lung cancer, MMP2 was reported to be implicated in the VEGFA expression by the tumor cells, through the PI3K/Akt pathway, underlining the major role played by MMP2 in the angiogenic process." (PMID 26921265, 2016). "Using patient-derived material, we observed that strong SRSF2 over-expression in NSCLC is associated with splicing alterations of the HER1/EGFR and VEGFA transcripts, as predicted from the results in the SRSF2-over-expressing H358 lung cancer cell line." (PMID 24428911, 2014). "Conversely, Egr-1, which is induced by ERK pathway activation, induces and enhances vascular endothelial growth factor-A (VEGF-A) in lung cancer." (PMID 25004251, 2014).
lung carcinoma (continued). "The critical role of VEGFA in tumor angiogenesis was further validated by its association with poorer prognosis in NSCLC patients, as revealed by Kaplan–Meier survival analysis involving 2166 lung cancer patients (kmplot.com)." (PMID 40940965, 2025). "The harmine derivative B-9-3 may exert its anti-NSCLC effects by inhibiting angiogenesis and promoting lung cancer cell apoptosis via the VEGFA/PI3K/AKT signaling pathway." (PMID 40432889, 2025). "Furthermore, early angiogenesis is essential for lung cancer cell metastasis and vascular endothelial growth factor A (VEGFA) inhibition induces long-term dormancy of lung cancer micrometastases by preventing angiogenic growth." (PMID 39998776, 2025). "Furthermore, VEGFA was identified as a key angiogenesis factor overexpressed in PM-adapted lung cancer cell lines (A549-PM, H1299-PM, and LLC-PM)." (PMID 40940965, 2025). "The levels of Tenascin C and VEGFA were higher in the MPE of EGFR-mutated lung cancer patients but not Fibronectin, ICAM-1, nor PAI-1." (PMID 37649596, 2023). "ADAMTS8 comes from integrins and metalloproteinases of the thrombospondin motif, and some studies show that ADAMTS8 is closely associated with vascular endothelial growth factor A (VEGFA), and some studies have found that ADAMTS8 expression in lung cancer is very low." (PMID 37409245, 2023). "Moreover, they stimulate vascular endothelial growth factor A (VEGF-A) and anti-apoptotic factor (B-cell lymphoma-2, Bcl-2) expression, thereby influencing the progression of lung cancer." (PMID 38044948, 2023). "Since the role of VEGFA in lung cancer was complicated, more independent experimental evidence was needed to support the hypothesizes about how VEGFA regulates metastasis and glucose metabolism." (PMID 35646922, 2022). "Further study indicates that vascular endothelial growth factor A (VEGFA) is a novel target of miR-101, and CAFs-derived VEGFA mediates the effect of miR-101 on migration and invasion of lung cancer cells, suggesting a new combination of VEGF and miR-101 for metastasis therapy." (PMID 36497343, 2022). "Similarly, changes in AS events in lung cancer will also affect the transcripts of VEGFA, MACF1, APP, and NUMB genes, thereby promoting the process of tumorigenesis." (PMID 36466711, 2022). "In contrast to the results that ALKBH5 positively regulated VEGFA expression in lung cancer cells, the mRNA stability data suggested that there may be a regulatory mediator between ALKBH5 and VEGFA." (PMID 36376862, 2022). "VEGFA regulates lung cancer migration and invasion by PI3K/AKT pathway." (PMID 34696659, 2022). "It is known that VEGF is an NFκB-inducible protein and is one of the most potent angiogenic factors crucial for tumor metastasis, and qRT-PCR analysis showed that VEGFA expression was remarkably upregulated in lung cancer cells with recombinant protein TNFSF12 treatment at 48 h." (PMID 34676217, 2021). "We next examined the role of VEGFA in lung cancer cell migration and invasion." (PMID 34977016, 2021).
lung carcinoma (continued). "The Peptibody vaccine could elicit high‐titer anti‐bFGF and anti‐VEGFA antibodies, which inhibited the proliferation and migration of Lewis lung cancer cell cells by decreasing the Akt/MAPK signal pathways." (PMID 32944017, 2020). "Researchers have also shown that CIN can predict which patients are most likely to benefit from specific treatments, such as bevacizumab (an anti-angiogenic monoclonal antibody targeting vascular endothelial growth factor A [VEGF-A]), a key drug used in the treatment of colorectal and lung cancers." (PMID 32235397, 2020). "However, Lee and colleagues showed that deguelin suppressed the growth of human lung cancer cells by down-regulation of HIF1α-mediated VEGFA expression in both normoxia and hypoxia conditions." (PMID 29416603, 2018). "Finally, we demonstrated that simultaneous high expression of ADAM9/VEGFA or ADAM9/ANGPT2 are linked to poor prognosis, which shows the clinical relevance of ADAM9-mediated vascular remodeling in lung cancer progression." (PMID 29118335, 2017). "In addition, miR-126 inhibits cell migration and invasion in lung cancer by targeting VEGFA and EGFL-7." (PMID 26274316, 2015). "Moreover, a transgenic mice model of the human vascular endothelial growth factor-A165 (hVEGF-A165) gene-induced pulmonary tumor was further treated with T1 for the in vivo lung cancer therapy test." (PMID 23662128, 2013). "Moreover, overexpression of ACE2 in cultured A549 lung cancer cells and in human lung cancer xenografs inhibited the cell growth and the vascular endothelial growth factor-a (VEGFa) expression induced by Ang II." (PMID 22319643, 2012). "MMP-2 is also upregulated in pathological conditions including cancer but like VEGFA is also elevated in normal processes including embryonic development and tissue remodelling so an increase in lung cancer specimens could be expected." (PMID 22593690, 2012). "In the lung cancer mouse model, M2-type TAMs could accumulate in well-differentiated tumor vascular sites, and promote tumor vascular reconstruction and recurrence by secreting vascular endothelial growth factor-A (VEGF-A)." (PMID 39654892, 2024). "Likewise, it is conceivable that miR-511-5p may mediate the functional role of LINC00173.v1 in the tumorigenesis of lung cancer cells since it directly targets VEGFA." (PMID 32473645, 2020). "Notably, SRSF2 over-expression modified HER1/EGFR and VEGFA expression in H358 lung cancer cells." (PMID 24428911, 2014). "In lung cancer, the YTHDC2/eIF4GI complex triggers cap-independent translation initiation, and targeted specific demethylation of VEGFA m6A significantly reduced VEGFA expression." (PMID 40316995, 2025). "In lung cancer, METTL3 binds to the A859 site within the internal ribosome entry site of VEGFA 5’UTR, recruiting YTHDC2/eIF4GI complex to promote VEGFA translation and increase its expression." (PMID 39098905, 2024). "Bevacizumab, a humanized monoclonal antibody to vascular endothelial growth factor A (VEGFA) and an anti‐angiogenic treatment, is an effective treatment for several malignant tumors including colorectal, ovarian, and non‐small cell lung cancer." (PMID 39440923, 2024). "We first analyzed the correlation of expression between PVT1 and VEGFA using the GEPIA website and found that they were significantly correlated with each other in lung cancer tissues." (PMID 36376862, 2022). "Lung cancer patient-derived EVs mRNA showed upregulation of SPP1, VEGFA, and POSTN as compared to lung cancer with bone metastasis patients." (PMID 36424413, 2022). "Based on transcript level expression study using quantitative real-time PCR showed five significantly differentially expressed genes SPP1, VEGFA, CD44, FOXO1 and POSTN in EVs cargo derived from lung cancer patients with bone metastasis." (PMID 36424413, 2022).